TNF (tumor necrosis factor)
Diseases named in the same sentence as TNF in open-access papers (continued):
Sharing a sentence is not in itself a finding about the gene and the disease.
COVID-19 (continued). "Multiple studies show high levels of proinflammatory cytokines such as IL-1, TNF, IFNs, IL-6, IL-8, IL-18, IL-17α, G-CSF, and GM-CSF, as well as chemokines, such as MCP-1, IP-10, MIP-1α, CXCL10, CCL2, CCL4, CCL14, CCL19, and CCL25 in severe cases of COVID-19." (PMID 40076291, 2025). "Conversely, anxiety may impact the function of five COVID-19 regulators, including the activation of four proteins (IL6, angiotensin 2, TNF, and IL10) and the inhibition of one protein (DPP4)." (PMID 40766923, 2025). "In COVID-19 patients, there were too much of certain proteins called cytokines, including IL-1β, IL-1RA, IL-7, IL-8, IL-9, IL-10, basic FGF, G-CSF, GM-CSF, IFN-γ, IP-10, MCP-1, MIP-1A, MIP-1B, PDGF, TNF-α, and VEGF." (PMID 40895261, 2025). "No patients treated with anti-TNF-alpha biological drugs plus methotrexate were vaccinated against flu and against COVID-19." (PMID 41395313, 2025). "To gain a comprehensive understanding of the demographic factors and laboratory biomarkers’ impact on ARDS in COVID-19, we conducted a correlation analysis between age, BMI, CRP, hematological biomarkers (neutrophil, lymphocyte, and NLR), and cytokines (IL-10 and TNF-α), with PaO2/FiO2." (PMID 40761632, 2025). "Considering the great importance of TNF, IL-1β, and IL18 in the pathogenesis of COVID-19, and in order to evaluate whether their levels were lower in mild cases than in severe cases, we analyzed their average expression levels in all groups of patients." (PMID 40141410, 2025). "Similarly, patients with severe COVID-19 were found to have high plasma levels of IL-10, MCP-1, and TNF-α." (PMID 39506759, 2024). "Indeed, significant correlations exist between levels of TNF-α, IL-6, IL-1β, IL-10, IFN-γ, and CCL2 with cognitive and behavioral changes in COVID-19 patients, thus showing generalized neuroinflammation." (PMID 39767737, 2024). "Some pro-inflammatory cytokines and chemokines, such as IL-6, IL-1, IL-18, and TNF-α, have been detected in high levels in patients with severe COVID-19 compared to non-severe cases." (PMID 39504070, 2024). "As TNF-α, while proinflammatory, also exhibits a tolerizing effect by desensitizing monocytes and macrophages to additional Toll-like receptor (TLR) stimulation, this likely helped limit excessive inflammation and promote faster COVID-19 resolution." (PMID 39408857, 2024). "Especially with respect to TNFα and IL-10, it was evident their concentrations were similar in both the COVID-19 patient groups with no cardiovascular co-morbidities and those with cardiovascular co-morbidities without statin use." (PMID 39518552, 2024). "There is research showing that cytokines closely related to cytokine storms (IL-6, TNF-α) and chemokines such as CXCL10 and CCL2 are significantly elevated in COVID-19 patients with diabetes, indicating that these patients are more prone to excessive inflammatory responses post-infection." (PMID 39654886, 2024). "Furthermore, Karki and Kanneganti observed a marked increase in TNF and IFN-γ levels in the sera of patients suffering from severe COVID-19." (PMID 39518964, 2024). "Although the prognostic value of TNF-α and IL-1β as therapeutic targets in COVID-19 is not known, they are important makers of disease severity in other infectious and inflammatory conditions." (PMID 36445625, 2024). "Similar to IFN-ɣ and IL-6 mRNA expression, TNF-α mRNA expression was significantly higher in the nasopharynx of COVID-19 patients than in non-infected subjects." (PMID 39339947, 2024). "Melatonin could resolve hyper-inflammatory conditions in COVID-19 and PASC by down-regulating proinflammatory cytokines (i.e., TNF-α, IL-1β, IL-6, and IL-8) and increasing anti-inflammatory cytokines such as IL-10660,661." (PMID 38555403, 2024). "Higher levels of D-dimer (p = 0.0306), NT-proBNP, IL-6, homocysteine, and TNF-α appeared in COVID-19 DM patients than in non-DM COVID-19 subjects, and these were found to be statistically significant (p < 0.0001)." (PMID 38675414, 2024).
COVID-19 (continued). "Previous studies have explored the correlation between serum levels of pro-inflammatory (IL-2, IFN-γ, TNF-α) or anti-inflammatory cytokines (IL-4 and IL-10) with clinical or negative outcomes in individuals with COVID-19." (PMID 38601541, 2024). "In another study, it was shown that plasma exosomes of COVID-19 patients contain double-stranded RNA (dsRNA) of SARS-CoV-2 and are responsible for the production of IL-6, IL-8, and TNF-α by mononuclear cells, particularly in CD4+ T cells, CD8+ T cells, and CD14+ monocytes." (PMID 39697632, 2024). "In addition to other pro-inflammatory cytokines, such as Tumor necrosis factor α (TNFα) and IL6, IL1β is also related to COVID-19 pathogenesis." (PMID 39346556, 2024). "Numerous studies have shown that non-anti-TNF-treated patients with IBD have equal immune responses following COVID-19 vaccination as healthy individuals." (PMID 39591144, 2024). "In univariable analyses, individuals with PASC tended to have lower levels of sCD14, IL10, IL17, IL1β, IL6 and TNFα compared to participants without PASC at 9–12 weeks after COVID-19 onset." (PMID 39008486, 2024). "Lastly, interleukins IL-1β, IL-6, and tumor necrosis factor plasma levels are elevated in PASC sufferers, and are also correlated to cognitive impairment in Alzheimer's disease, and with severity of hyposmia after COVID-19." (PMID 39839305, 2024). "Previous observational studies have presented evidence suggesting a possible link between the usage of anti-TNF medications and a lower probability of having negative events related to COVID-19." (PMID 39459457, 2024). "The serum IL-6, IL-1β, and TNF-α expression levels were measured by RT-PCR in COVID-19 patients (n = 41), stratified into non-survivors (n = 23) and survivors (n = 18), and in the serum of subjects in the control group (n = 20)." (PMID 39201618, 2024). "Infliximab, a TNF-α inhibitor, was shown to lower 28-day mortality in a selected group of patients with COVID-19, suggesting a role of TNF-α in the pathogenesis of more severe COVID-19." (PMID 38985797, 2024). "Furthermore, the cytokines TNF and IFN-γ serve as triggers for initiating PANoptosis and are known to exacerbate COVID-19." (PMID 39205235, 2024). "Additionally, studies have demonstrated that severe COVID-19 cases may trigger a cytokine storm, characterized by an overactive T lymphocyte immune response and elevated levels of pro-inflammatory cytokines, such as interleukin 6 (IL-6) and tumor necrosis factor-alpha (TNF-α)." (PMID 40735669, 2024). "Moreover, in COVID-19 patients, increased mRNA expression levels of CXCL10, CCL2, and TNF were correlated with an increased number of MKs27,28." (PMID 38519457, 2024). "The group with severe/critical COVID-19 had more abnormalities in many laboratory indicators, including lower levels of autophagy markers (BECN1 and ATG7) and vitamin D, and higher levels of inflammatory markers (TNF-α and IL-1β)." (PMID 38783947, 2024). "CoQ10 is also a potent anti-inflammatory agent that effectively down-regulates cytokines (i.e., TNF-α, IL- 6, CRP) and could optimize viral-disrupted ACE2/RAAS system, by exerting anti-angiotensin II effects and decreasing OxS in COVID-19 patients." (PMID 38555403, 2024). "However, TNF antagonists should be delayed for 2 weeks upon infection with SARS-CoV-2 and even discontinued during acute illness due to COVID-19." (PMID 39538233, 2024). "In this first study of its kind designed to assess the impact of RIC on inflammatory cytokines in participants admitted to hospital with COVID-19, we were unable to detect a significant reduction by RIC in levels of pro-inflammatory cytokines (including IL-1β, IL-6, and TNF-α)." (PMID 36445625, 2024). "Soluble immune mediators such as TNF-α and interferons produced during viral infections, including SARS-CoV-2, damage the intestinal epithelium, especially when the inflammatory response is sustained as in patients with severe COVID-19 (70, –, 72)." (PMID 39345212, 2024).
COVID-19 (continued). "This is a clear demonstration of productive SARS-CoV-2 infection of primary human macrophages and a direct association between natural infection of these cells and production of the pro-inflammatory cytokines characteristic of severe COVID-19 (CXCL9 and −10, IFNα, IL-6 and TNFα)." (PMID 39737903, 2024). "TNF-α and IFN-γ shock mirrors cytokine storm syndromes, including COVID-19." (PMID 38727220, 2024). "In the present study, higher levels of STING and cGAS gene expression and plasma levels of IFN-α, IL-6, and TNF-α were identified in patients with the severe form of acute COVID-19 than in patients with the nonsevere form." (PMID 38424312, 2024). "While our study did not analyze immune seroconversion in response to mRNA COVID-19 vaccination, we also found increased risk of acquiring SARS-CoV-2 infection in PsD patients treated specifically with the TNF-α inhibitor etanercept." (PMID 38793704, 2024). "At 9–12 weeks after disease onset, participants who had initially severe COVID-19 tended to have significantly higher levels of IP10 and sCD163 and lower levels of IL10, IL6, TNFα, IL17 and IL13 compared to those with mild or moderate disease, when adjusting for other covariates." (PMID 39008486, 2024). "The release of proinflammatory cytokines, i.e., TNFα, IL-6, and IFN-β, and the durable increase in activated monocytes and plasmacytoid dendritic cells, promote a state of persistent inflammation in patients with long-term COVID-19 symptoms." (PMID 39124710, 2024). "Higher concentrations of IL-2, IL-6, IL-8, and TNF-α were also reported in ICU patients with COVID-19 in comparison to non-ICU patients." (PMID 38707035, 2024). "Comparison of the MPO, ADA, CCL22, TNFα, and IL-6 mRNA expression between patients with and without completion of COVID-19 vaccines did not reveal any statistically significant differences." (PMID 36482706, 2023). "TNFα but not IL-6 or IL-10 levels were increased in mild COVID-19 patients, compared to healthy controls." (PMID 36509969, 2023). "Mimicking systemic inflammation as it occurs during COVID-19 by pre-stimulation of EECM-BMECs with TNFα/IFNγ still failed to allow for productive infection of EECM-BMECs with SARS-CoV-2." (PMID 37875964, 2023). "In support of this hypothesis, a recent study found that COVID-19 patients had reduced upregulation of CD80 on monocytes and abrogated release of IL-6, TNF, IL-1a and IL-1b in response to Candida albicans." (PMID 38169876, 2023). "Among the cytokines analyzed in response to S-peptide, some of them such as TNFα, IL-6, IL-2, IFNγ, or CXCL10 were differentially produced between naïve subjects and subjects recovered from COVID-19 early after the second vaccination dose (sample 2), with higher levels in the former group." (PMID 37153580, 2023). "It has been reported that TNFα and INFγ can act synergistically to trigger inflammatory cell death in vitro and in vivo, which mimics the SARS-CoV-2-induced cytokine shock syndrome (CSS) that occurs in COVID-19 patients." (PMID 37459541, 2023). "However, TNFα/IFNγ-induced death in mice occurs within hours, whereas death from acute respiratory distress syndrome (ARDS) in COVID-19 patients happens over a much longer time." (PMID 37459541, 2023). "The strength of our study lies in the comprehensive dynamics of the pro-inflammatory (mainly IL-1β, IL-6, IL-8, TNF-α) and anti-inflammatory (IL-10) cytokines over time and their comparison with non-severe COVID-19 cases as supporting evidence." (PMID 37384050, 2023). "TNF-α levels were increased in both bacterial pneumonia and COVID-19 groups, although this difference was not statistically significant (P=0.316)." (PMID 38585537, 2023). "Tumor necrosis factor (TNF)-α, interleukin (IL)-1, IL-6, interferon (IFN)-γ, IL-17A and IL-8 are among the pro-inflammatory cytokines that have been mostly studied in patients with COVID-19." (PMID 36875710, 2023).
COVID-19 (continued). "Significant decreases in plasma concentrations of the pro-inflammatory cytokines IL-6, TNF, and IFN-γ, the leukocyte chemoattractants CXCL8, CXCL10, and CCL2, and the anti-inflammatory cytokines IL-10 and IL-1Ra were observed in COVID-19 patients during dexamethasone treatment." (PMID 37614228, 2023). "The levels of IL-6 (p= 0.0300) and TNF-α (p = 0.0800) were higher in patients with severe COVID-19 than in those with the non-severe form." (PMID 37138871, 2023). "The mediators CCL3, CCL4, CCL2, CCL5, IL-12, IL-15, IL-1Ra, and PDGF were higher in healthy volunteers, while the mediators CCL11, CXCL10, IL-1b, IL-6, TNF-a, IFN-g, IL-17, IL-9, IL-10, IL-13, FGF-basic, G-CSF, GM-CSF, IL-7, and IL-2 were increased in COVID-19 positive patients." (PMID 37903875, 2023). "Moreover, it was revealed that children with PIMS-TS have higher levels of IL-6, IFN-, TNF-, and CXCL10 (chemokine “C-X-C motif” ligand) than children with acute COVID-19." (PMID 36839601, 2023). "On the other hand, when PBMCs were stimulated with LPS, the relative production of IL-6 cytokines was lower in the post-COVID-19 group (ES = 0.75) and TNF-α was not different between the groups." (PMID 37753077, 2023). "In contrast, in accordance with previous studies that found that the respective treatments do not significantly impair COVID-19 vaccination efficacy, we observed a decrease in CFRs for patients under anti-TNFα, JAK inhibitor, or thalidomide analog treatment." (PMID 37397473, 2023). "Components of the COVID-19 cytokine storm (IL-6, TNF-α, and IL-1) have been implied to stimulate ATX expression and/or activity in various cell types and vice versa, LPA has been reported to stimulate TNF and IL-6 expression in various contexts." (PMID 36851766, 2023). "IL-6, TNFα, and IL-10 levels were highest in severe and critical COVID-19 patients, with comparable levels to non-COVID-19 critical patients." (PMID 36509969, 2023). "Higher levels of circulating IL-6, IL-10, IL-8, and tumor necrosis factor-alpha (TNF-α) were detected in non-survivors compared to survivors as well as in severe or critical COVID-19 cases." (PMID 37896963, 2023). "Moreover, p62 modulation by NSP5 and ORF3a in vitro was involved in the regulation of TNF, IL-1, IL-6, IL-10, and IL-33 mRNA expression in THP-1 monocytic cell line, indicating a proinflammatory role of this autophagy receptor in COVID-19." (PMID 37174682, 2023). "As expected, the increased intracellular production of TNF-α is observed in patients in clusters I and III and more significantly in patients with fatal outcomes compared to surviving patients with severe COVID-19 in cluster I." (PMID 37342247, 2023). "Levels of TNF-α, IL-1Ra, IL-6 and IL-18 were also higher in HD + COVID-19 than in HD patients, without reaching statistical significance." (PMID 36675231, 2023). "It has already been described that patients treated with anti-TNFα exhibited lower serologic responses one month and six months after vaccination (COVID-19 BNT162b2) compared to those not treated with anti-TNFα or to healthy controls (HCs)." (PMID 37047412, 2023). "The TNF-α and IFN-γ are related to cytokine storm-induced mortality in patients with COVID-19." (PMID 37189696, 2023). "Acute COVID-19 children had significantly elevated levels of cytokines, (Interferon (IFN)) IFNγ, Interleukins (IL)-2, TNFα, IL-1α, IL-1β, IFNα, IFNβ, IL-6, IL-12, IL-17A and Granulocyte-Colony Stimulating Factors (G-CSF) in comparison to convalescent COVID-19 and controls." (PMID 37013538, 2023). "Studies had shown that PTEN can activate dendritic cells, B cells and T cells, which are innate immune cells, and secrete pro-inflammatory factors, including interferon (IFN), TNF-α and IL10, thus inducing the formation of the cytokine storm in patients with COVID-19." (PMID 37037848, 2023).
COVID-19 (continued). "Of note, nutritional glutamine supplementation caused a decrease of IL-1β, TNF-α and high-sensitivity C-reactive protein (hs-CRP), in COVID-19 patient sera, compared to the non-supplemented control group." (PMID 36984782, 2023). "Anti-TNF-α antibodies, ustekinumab, and IL-17 inhibitors are suggested as preferred targeted therapies in these patients (without heart failure) in the COVID-19 era." (PMID 38029150, 2023). "Patients with COVID-19 had substantially greater levels of ACE2, IL-6, TNF-α, glucose, total white blood cells (WBCs), neutrophils, NLR, platelets, mean corpuscular hemoglobin (MCH), and mean corpuscular hemoglobin concentration (MCHC) than the healthy participants." (PMID 37240319, 2023). "The lethal shock phenotype observed in mice administrated with TNF-α and IFN-γ combination mirrors the cytokine storm syndrome in patients with severe COVID-19, emphasizing the link between the dysregulated release of cytokines and the multiorgan damage in patients with SARS-CoV-2 infection." (PMID 36776881, 2023). "However, HD patients with COVID-19 symptom worsening showed up-regulation (more than 2.5-fold increase) of GM-CSF, IFN-γ, IL-1β, IL-2, IL-6, IL-17A and IL-21, and down-regulation of TNF-α and IL-8 serum levels after the dialysis procedure." (PMID 36675231, 2023). "To determine the effect of COVID-19 and vaccines on human health, we examined serum levels of ACE2, CTSL, AngII and TNFα in hospitalized adult patients 14 days after the onset of COVID-19 infection, healthy controls and subjects vaccinated with two doses of COVID-19 mRNA vaccines." (PMID 38137381, 2023). "In addition to TNF-α, the levels of the adhesion molecules ICAM-1 and E-selectin were greatly increased, especially in female COVID-19 patients." (PMID 37896963, 2023). "Furthermore, serum levels of TNF-α, IFN-γ were significantly elevated in COVID-19 patients with critical case compared to mild and severe stage." (PMID 37283736, 2023). "PAL was also associated with modulation of the peripheral frequency of Treg cells and the expression of PD-1 in CD8+ T cells, although it abrogated the statistical effect in the analysis of TNF-α and IL-6 production by LPS- and PMA-stimulated PBMC of post-COVID-19 patients." (PMID 37753077, 2023). "Additionally, the PCA coordinates obtained from the 3rd trimester demonstrated that several soluble mediators were vectors related to convalescent COVID-19 in pregnant women, except for CXCL10, IL-1β, TNF-α, IFN-γ, PDGF and GM-CSF." (PMID 37122732, 2023). "An interesting observation is that 80% of septic patients have hypophosphatemia associated with elevated concentrations of inflammatory cytokines such as tumor necrosis factor (TNF) alpha and interleukin (IL)-6 and other inflammatory cytokines included in cytokine storm in COVID-19." (PMID 37568451, 2023). "The immune response in COVID-19, which may result in ARDS, involves the unbalanced secretion of various inflammatory cytokines and chemokines, including TNF-α, IL-1β, IFN-γ, IL-6, IL-10, IL–1RA, IP–10, MCP–1, and IL-8 (CXCL8)." (PMID 37600829, 2023). "The downregulation of the NF-κB/MAPK signaling pathway was postulated to decrease pro-inflammatory cytokines such as IL-6, TNF-α, IL-1β, CXCL10/IP-10, CCL2/MCP-1, and IL-8, suggesting that it may prevent cytokine storm in COVID-19." (PMID 37298539, 2023). "TNF-a and IFN-γ are also important inflammatory cytokines that provide good targets for cytokine storm control, and clinical trials to evaluate these blockers in COVID-19 (ChiCTR-2000030089 and NCT-04324021) are continuing." (PMID 37124230, 2023). "Additional studies have also revealed that patients with severe COVID-19 have a significantly elevated cytokine profile of IL-2, IL-6, IL-7, IL-10, IP-10, MCP-1, TNF-α, macrophage inflammatory protein 1 alpha, and granulocyte-CSF compared to patients with mild to moderate COVID-19." (PMID 37457959, 2023).